FANCD2 (FA complementation group D2)
Diseases named in the same sentence as FANCD2 in open-access papers (continued):
Sharing a sentence is not in itself a finding about the gene and the disease.
tumor (continued). "We suggested that STARD14 may achieve the regulation of ferroptosis in LUAD by promoting the expression of CDKN1A and FANCD2, ultimately contributing to tumor progression." (PMID 37790851, 2023). "Therefore, we further investigated the relationship between FANCD2 expression and tumor immunity in LUAD." (PMID 35646059, 2022). "EZH2, TUBG1, and PPM1G are related to the ferroptosis gene, FANCD2, and may be involved in tumor biological behaviors mediated by ferroptosis." (PMID 36686830, 2022). "The function of FANCD2 may include tumor ferroptosis and DNA damage, and cell cycle, which influence the outcome of LUAD together." (PMID 35236309, 2022). "In addition, we demonstrated that FANCD2 expression was positively correlated with several tumor-infiltrating lymphocytes (TILs) and multiple immune-associated signatures in GBM." (PMID 35754466, 2022). "Tumor cells with low FANCD2 expression undergo ferroptosis easily." (PMID 35646059, 2022). "To investigate whether FANCD2 is a predictive biomarker for immunotherapy efficacy, we evaluated the relationship between FANCD2 and outcomes by the tumor immune dysfunction and exclusion (TIDE) score." (PMID 36267413, 2022). "Interestingly, our previous ESCC functional study demonstrating that FANCD2 depletion significantly inhibited tumor growth and metastasis, already showing that DNA damage repair is essential for ESCC progression." (PMID 34206946, 2021). "Although FANCD2 was not up-regulated in TMZ-insensitive U251 cells according to the GSE100736 dataset, but FANCD2 was highly expressed in GBM tumor tissues, it was a ferroptosis-related gene, and FANCD2 overexpression improved the viability of TMZ-treated U87 cells." (PMID 34689169, 2021). "Analysis of gene expression, mutation, DNA methylation, and prognostic value in LUAD revealed CISD1, ATP5MC3, PGD, SLC7A11, ACSL3, and FANCD2 to be significantly upregulated in LUAD and elevated expression of these FRGs to be associated with advanced tumor stage and poor prognosis." (PMID 35320929, 2021). "Utilizing Clustered Regularly Interspaced Short Palindromic Repeat (CRISPR) technology, FANCD2 knockout models were established to examine the functional impact in mouse models for tumor growth and metastasis and in vitro assays for cell growth, cell cycle, and cellular localization." (PMID 32906798, 2020). "Taken together these findings suggest that cytoplasmic activity of FANCD2 might play an important role in regulating its anti-tumor properties." (PMID 32165999, 2020). "WES finding of FANCD2 mutations might help explain the intriguing result of our PDX model, namely the possible re-sensitization of tumor cells to the original cisplatin regimen." (PMID 32957974, 2020). "The specific HRR mutations identified in the 21 tumour samples were: BRIP1 (n = 5), CDK12 (n = 3), RAD54L (n = 2), RAD51B (n = 2), RAD54L rearr (n = 1), ATM rearr (n = 1), FANCA rearr (n = 1), FANCD2 (n = 1), FANCL rearr (n = 1), FANCL (n = 1), RAD51C (n = 1), RAD52 del (n = 1), XRCC3 rearr (n = 1)." (PMID 30353044, 2018). "Based on our present study, the prominent long-known form of FANCD2 (V1) may in fact signify abnormality, in the context of tumor suppression, and has mistakenly been considered normal." (PMID 28157704, 2017). "Similarly, we observed six homozygous deletions over VHL, five of which take out the nearby tumour suppressor FANCD2 as well." (PMID 29089486, 2017). "Our data show that this variant of FANCD2 exhibits greater association with non-malignant cells compared to malignant cells and properties of a potent tumor suppressor." (PMID 28157704, 2017). "Deficiencies in Rad18, FANCD2, BRCA2, and Rad51 are all known to sensitize tumor cells to CPT." (PMID 26871286, 2016).
tumor (continued). "Finally, using an RNA interference approach in FA-D2 patient cells and PTEN-deficient tumor lines, we demonstrate that PTEN and FANCD2 function epistatically during ICL repair." (PMID 27819275, 2016). "Interestingly, the patient's grade III tumour exhibited increased FANCD2 expression compared to the previous biopsy proven lower grade disease." (PMID 25071006, 2014). "Collectively, ΔNp63 elevation is associated with an impaired status of the FA pathway, and it may act as a tumorigenic mediator of inactivated FANCD2 during tumor development." (PMID 23965832, 2013). "Our study thus far reveals that the regulation of ΔNp63 expression by an inactivated FANCD2 may play important roles in the tumor promotion potential resulting from an impaired FA pathway." (PMID 23965832, 2013). "We observed a significant increase in tumor incidence and severity of neoplastic disease in the K14E6E7/FancD2-/- mice compared to the K14E6E7/FancD2+/+ mice; however, fancD2-deficiency did not increase either readout for tumorigenesis in the K14E6 mice expressing E6 alone." (PMID 24086435, 2013). "Activation of FANCD2 monoubiquitination in peripheral blood lymphocytes or tumor cells during clinical trials may allow an internal measurement of CHK1 inhibition in vivo." (PMID 19371427, 2009). "Our results indicated that HMGA1 recruited FANCD2 to promote DNA replication and cell cycle progression both by attenuating R-loop-induced replication stress and by protecting stalled replication forks from degradation, ultimately enhancing tumor resistance to chemotherapy and irradiation treatment." (PMID 40288645, 2025). "While this patient is unlikely to require PARPi due to the tumor type and current absence of metastatic process, it is of interest for other patients and tumor types whether FANCD2 mutations should be routinely tested as a PARPi biomarker." (PMID 39768544, 2024). "In addition, downregulated FANCD2 significantly inhibits tumor growth in nude mice." (PMID 35646059, 2022). "The high expression level of FANCD2 was associated with an advantaged TNM stage, a less chemotherapy sensitivity, a low ImmuneScore, which indicated a deactivation status in an immune microenvironment, a high tumor mutation burden, and poor survival for LUAD patients." (PMID 35236309, 2022). "Surprisingly, this new revelation may indicate that the long-known form of FANCD2, V1, might be somewhat “oncogenic” owing to its relatively high expression levels in malignant cells/tissues, in conjunction with inefficient tumor suppressive activity compared to V2." (PMID 28157704, 2017). "However, PAS is shown here to be an essential factor in determining the tumor suppressor function of the FA pathway, because the newly recognized version of FANCD2 (V2) appears to have tumor-suppressor function more potent than the version we have known for decades (V1)." (PMID 28157704, 2017). "Furthermore, expression levels of FANCD2 strongly correlate with tumour grade." (PMID 25071006, 2014). "This suggests that the regulation of ΔNp63 expression by inactivated FANCD2 may play an important role in the development of human tumors, presumably starting from tumor initiation to tumor mass development, which often leads to hypoxic conditions within solid tumors." (PMID 23965832, 2013). "Thus, inhibition of FANCD2 monoubiquitylation (FANCD2-Ub), a key step in the FA pathway, might target tumor cells defective in ATM through synthetic lethal interaction." (PMID 20043851, 2009). "The results revealed that in tumor tissues from ccRCC patients, POLQ expression positively correlated with the expression of CDC6, CDC45, CDT1, FANCD2, and MCM2." (PMID 38270643, 2024). "Our findings revealed a marked increase in FANCD2 promoter methylation within ESCA, KIRC, and LUSC tumor tissues when compared to their respective normal counterparts." (PMID 38443946, 2024).
tumor (continued). "In this study, we identified FANCD2 expression had a strong correlation with B cell, Neutrophil, TMB, and PD-L1 in PAAD, which was closely related to tumor immunity." (PMID 37369808, 2023). "For example, the expression of SLC7A11, FANCD2, and CISD1 was higher in tumor tissues than that in normal tissues, but ATP5MC3 was lower." (PMID 35309947, 2022). "In summary, five of the genes (CARS1, CHAC1, FANCD2, G6PD, and HMOX1) in the prognostic model have been reported to contribute to ferroptosis and to be upregulated in BC tumor tissue, in contrast to AIFM2." (PMID 36313179, 2022). "OncoKB and COSMIC database screening identified 36 tumour-related genes including BRCA2 and FANCD2 in all groups." (PMID 36686473, 2022). "In KPLU tumors, the overall protein abundance of the FA proteins FANCD2 and FANCI were significantly reduced compared to USP28-proficient tumor samples, demonstrating that the USP28-∆Np63 axis maintains FA expression in vivo." (PMID 34611298, 2022). "POLQ/FANCD2 single/double KO and control KYSE180TS/SLMT cells were injected into both flanks of the mice and the tumor volumes were measured weekly for 3 consecutive weeks." (PMID 34206946, 2021). "Four ferroptosis driver genes FLT3, ALOX12B, ALOX15, and VDAC2, had a low CNV, and four ferroptosis suppressor genes ACSL3, CISD1, FANCD2, and SLC3A2, had a high CNV, indicating that ferroptosis was inhibited in tumor development." (PMID 34434214, 2021). "DDX47 is involved in maintenance of genome stability via interacting with FANCD2 to lower R-loop levels 28, and study has revealed that overexpression of DDX47 induces tumor cells apoptosis." (PMID 33456353, 2021). "Since both POLQ and FANCD2 are DNA damage repair genes conferring tumor progression, we explored the possible synergistic or synthetic lethality relationships between POLQ and FANCD2 in ESCC tumorigenesis." (PMID 34206946, 2021). "Down-regulation of lncRNA TMEM161B-AS1 and/or over-expression of hsa-miR-27a-3p down-regulated the expression of FANCD2 and CD44, and inhibited the tumor growth in nude mice." (PMID 34689169, 2021). "For many FA or FA-related proteins upstream of the ID complex, their variants will, to some extent, impair the monoubiquitination of FANCD2 and FANCI and thus the tumor suppressive roles of FA signaling." (PMID 34884777, 2021). "According to the CGGA database, the expression levels of FANCD2 and CD44 were positively correlated with the grade of the tumor." (PMID 34689169, 2021). "Our model is able to reject local fragility for 13 of the 15 peaks containing known tumour suppressors, VHL/FANCD2 and CDKN2C being the exceptions." (PMID 29089486, 2017). "In response to DNA damage mediated by HU and MMC, both FANCD2 mono-ubiquitination and FANCM phosphorylation were detected in tumor cells transfected with control siRNA (lanes 4, 7)." (PMID 26625197, 2016). "We analyzed the ROC curves for all previously known potential factors, including age, tumor size, hemoglobin, along with our potential markers: BRCA1, BRCA2, RAD51, FANCD2, BLM and BRIP1." (PMID 24708616, 2014). "This tumour was graded WHO II at biopsy later that year and immunohistochemical analyses revealed weak FANCD2 expression." (PMID 25071006, 2014). "Surprisingly, that study also showed that let-7 represses several tumour suppressor genes (BRCA1, BRCA2, FANCD2, and PLAGL1, among others) and checkpoint regulators (CHEK1, BUB1, BUB1B, MAD2L1, and CDC23, among others)." (PMID 20179807, 2010).
tumor (continued). "Inhibition of FA signalling components—such as FANCL, UBE2T or FANCD2—has been shown to sensitise tumour cells to crosslinking agents without inducing catastrophic genomic instability." (PMID 41486508, 2026). "Bulk tumour cells and both AR and CD24low/CD44+ BCSCs effectively sensed cisplatin-ICLs, mounting a comparably robust FA/DSB response following pulse cisplatin treatment (2 h), as evidenced by FANCD2 and initial 53BP1 recruitment respectively." (PMID 39695328, 2025). "Furthermore, while 2-DG, MMC or olaparib alone partially inhibited orthotopic tumor growth of FANCD2-KD SCC23 cells, 2-DG plus MMC or olaparib drastically inhibited the tumor growth of FANCD2-KD SCC23 cells in vivo." (PMID 39117659, 2024). "Additionally, FANCD2 acts as an autonomous prognostic indicator for LUAD, exhibiting considerably elevated levels of expression in tumor tissues compared to their normal counterparts." (PMID 38443946, 2024). "The top-scoring genes altered in the four gene sets included many genes associated with cell apoptosis and DNA damage, such as GADD45A, DDIT3, BAX, CASP1, CASP8, ATM, and FANCD2, demonstrating that diminishment of RAD51 contributes to the tumor suppressive effect." (PMID 37175611, 2023). "In contrast, FANCD2, PTGS2, SLC2A1, and SQLE were higher in tumor compared to normal tissues." (PMID 36733386, 2022). "Furthermore, the results of immunohistochemistry suggested that eIF5A was significantly reduced (g), and the ferroptosis marker proteins (FANCD2, SLC7A11, and HSPb1) were significantly downregulated in the tumor tissues of sh-eIF5A group mice (h)." (PMID 35874632, 2022). "Similarly, tumour tissue explants revealed a significant reduction in USP28 and FANCD2 upon treatment with AZ1." (PMID 34611298, 2022). "Furthermore, FANCD2 recruits immunosuppressive cells into the TME and regulates the expression of corresponding immune markers to weaken the anti-tumor immune response." (PMID 35646059, 2022). "Third, the functions of FANCD2 in ferroptosis and tumor immunity, as well as their mechanism, have not been clarified in vitro or in vivo." (PMID 35646059, 2022). "Immuno-histochemical analysis of tumor-bearing lungs from murine SCC transplant animals revealed that in control treated animals USP28 and its substrate ∆Np63 were detectable, along with the ∆Np63 target FANCD2." (PMID 34611298, 2022). "As ferroptosis plays crucial roles in both immunity and pulmonary carcinogenesis, the correlation between CISD1, FANCD2, PGD, ASCL3, ATP5MC3, and SLC7A11 expression and tumor immune infiltration in LUAD was evaluated utilizing data obtained from the TIMER database." (PMID 35320929, 2021). "In our earlier studies, we discovered that a new form of FANCL protein, named FAVL, dysregulates the FA signaling in non-FA human tumor cells and acts as a tumor promoting factor by inactivating FANCD2 and FANCI/the ID complex." (PMID 34884777, 2021). "However, FANCD2, SLC7A11, GLS2, DPP4, and ALOX15 were obviously suppressed in grades 1–3 of tumor samples compared to normal tissues." (PMID 34531924, 2021). "Assessing the number of nuclear foci of RAD51, FANCD2 and γH2AX may help to establish DDR cellular competence, before, during and after treatment with IR and PARP inhibitors, to predict tumor sensitivity or acquired resistance to treatments." (PMID 27884198, 2016). "Our recently developed FATSI method to evaluate FANCD2 foci formation, which is capable of evaluating the functionality of the pathway using FFPE tumor samples could represent such a test." (PMID 25566506, 2014). "Although proteins such as FANCD2, PCNA, notch receptor, and histones H2A and H2B were reported to be deubiquitinated by the WDR48·DUB complex, the cellular functions of WDR48 and its role in tumor suppression were not completely known." (PMID 24145035, 2013).
tumor (continued). "Additionally, it has been proposed that FANCD2 may protect the genome from unrestricted resection by DNA2, which results in chromosomal rearrangements and tumor aneuploidy." (PMID 39768544, 2024). "Without FANCD2, tumor proliferation stalls; however, early on in tumor development, its damage might provide genomic instability required for tumor development and evolution." (PMID 39768544, 2024). "FANCD2 could be an effective for prognostic recognition, immune efficacy evaluation, and mRNA vaccine for patients with PAAD, providing a vital guidance for further study of regulating tumor immunity and vaccine development." (PMID 37369808, 2023). "FA proteins such as FANCD2 and FANCM are involved in the regulation of this balance by resolving or inhibiting the formation of telomere secondary structures to stabilize stalled replication forks and promote break-induced repair (BIR) to maintain the survival of ALT tumour cells." (PMID 35205225, 2022). "FANCD2 may prevent erastin-induced GPX4 degradation and reduce tumour sensitivity to ferroptosis." (PMID 34095228, 2021). "Our results indicate that the enhancement effect of FANCD2 depletion combined with CHK1 inhibitor in sensitizing the LCS cells to gemcitabine supports the FA pathway and CHK1 as two therapeutic targets for improvement of anti-tumor regimens in treatment of LSC." (PMID 29118324, 2017). "In addition, FANCM phosphorylation did not occur and FANCD2 mono-ubiquitination was significantly reduced in tumor cells transfected with FoxF1-specific siRNA (lanes 5, 8)." (PMID 26625197, 2016). "Furthermore, ferroptosis-related genes with copy number amplification (including FADS2, NQO1, ABCC1, ACSF2, HMOX1, FANCD2 and SQLE) demonstrated higher expression in tumour tissues, and those with copy number deletion (including CRYAB, ACSL3, ZEB1) demonstrated lower expression in tumour tissues." (PMID 35145965, 2022). "This scenario was based on key studies by the Lambert laboratory where sustained SCC growth in Fancd2 knockout mice occurred even in the absence of the viral E7 oncogene, perhaps due to virally induced DNA damage accumulation and rapid selection for oncogene-independent tumor growth." (PMID 30589865, 2018). "Some FA proteins, including FANCD2, have also been shown to play a role in the alternative lengthening of telomeres (ALT), a telomere maintenance process independent of telomerase that relies on HR present in some tumor cells." (PMID 31167143, 2019). "For other known tumour suppressor loci, CDKN2C and FANCD2/VHL, our model could not identify this signature." (PMID 29089486, 2017).